CAT (catalase)
Diseases named in the same sentence as CAT in open-access papers (continued):
Sharing a sentence is not in itself a finding about the gene and the disease.
tumor (continued). "Furthermore, tumor-produced ROS likely caused NK cell dysfunction in chronic myelogenous leukemia (CML), since catalase could restore NK cell cytotoxic capacity against primary tumor cells obtained from patients affected with this malignancy." (PMID 32630174, 2020). "This cross-talk between tumor cells and CAFs could be abrogated with the addition of catalase." (PMID 31426364, 2019). "However, primary 1O2 can utilize tumor cells like a switchboard, on which it triggers the sustained generation of “secondary 1O2” [The term “secondary1O2” is used in this paper for1O2that is generated by tumor cells after they have been triggered through local catalase inactivation by primary1O2]." (PMID 31558835, 2019). "In addition, the expression and activity of endogenous antioxidant scavenging enzymes (superoxide dismutase, glutathione peroxidase, catalase, and glutathione-S-transferase) in the cells of normal and tumor-bearing animals were increased in blood, liver, and tumor tissue." (PMID 30186541, 2018). "Similarly, our data showed that CAT was downregulated in chemoresistance samples, which might exacerbate local microenvironment to strengthen tumor chemoresistance through the way of hypoxia, subsequent acidosis, and the like." (PMID 29850522, 2018). "Additionally catalase may affect the mechanism of multidrug resistance and protect tumor cells against the induction of apoptosis." (PMID 29707141, 2018). "Therefore, hydrogen peroxide accumulation due to increased SOD and reduced CAT activities may contribute to tumor cell proliferation." (PMID 30420941, 2018). "Notably, tumor growth was attenuated by catalase in the microenvironment." (PMID 28102840, 2017). "Therefore, in the circumstances of both tumor hypoxia and an abundance of anti-oxidative enzymes, such as many kinds of peroxidases and catalase, in tumor tissues, the therapeutic effects of X-rays and electrons are decreased to one-third of their ideal efficacy." (PMID 27043633, 2016). "Catalase-mediated protection from intercellular ROS signaling was found in all human cancer cell lines studied so far (more than 70 cell lines), indicating that this might be an important mechanism for tumor survival." (PMID 26682014, 2016). "However, the therapeutic effect of radiotherapy using a Linac for relatively large tumors of more than several centimeters in diameter decreases to one-third of that of smaller tumors due to tumor hypoxia and the abundance of anti-oxidative enzymes, such as many kinds of peroxidases and catalase." (PMID 27043633, 2016). "In vivo, HA-MSN-CDDP effectively suppressed tumor growth, mitigated lipid peroxidation, and preserved antioxidant enzyme activities (SOD and CAT) in major organs." (PMID 41754914, 2026). "Conversely, tumor tissues exhibited significantly reduced expression of FDX1, CAT, and EHHADH than normal (p < 0.05)." (PMID 40109870, 2025). "So, based on these assumptions, this study highlights the central role of oxidative stress in the pathogenesis of LSCC, focusing on the expression of six key proteins involved in antioxidant defense and tumor biology: SOD, CAT, HO-1, NRF-2, MT, and VIM." (PMID 40149643, 2025). "This system employs a self-sustaining enzymatic cascade: CAT alleviates hypoxia by converting tumor-derived H2O2 into oxygen, while LOX depletes lactate and generates additional H2O2 to fuel CAT activity, synergistically amplifying ROS production." (PMID 40704016, 2025). "For example, engineering CAR T-cells to co-express antioxidant enzymes, such as catalase (CAT), which scavenges hydrogen peroxide (H2O2), has been reported to reduce T-cell exhaustion and improve anti-tumor activity." (PMID 40298832, 2025). "Immunohistochemical database analysis reveals that EIF4EBP1, RIMKLA, and BIRC5 are highly expressed in tumour tissues, while the PCK1, PLG, PEBP1, and CAT show a lower expression in tumour samples." (PMID 40591061, 2025).
tumor (continued). "Using a self-assembly system of lysozyme and cysteine, we co-loaded glucose oxidase (GOx) and catalase (CAT) in a one-step process, aiming to simultaneously achieve dual functions of anti-tumor recurrence and anti-postoperative adhesion." (PMID 40358287, 2025). "EAC tumor burden significantly (p < 0.05) depleted antioxidant defenses, reducing GSH (54.3%), SOD (43.8%), and CAT (65.5%) levels while elevating lipid peroxidation (MDA: + 102.5%) compared to normal controls." (PMID 41326498, 2025). "In “cold” tumor models, for example, a multifunctional nanotherapeutic system including GF-Ala, catalase, and the TLR7/8 agonist R848 in a PEG-PLGA matrix demonstrated significant TME remodeling, tumor regression, and inhibition of metastases." (PMID 40872479, 2025). "Increased antioxidant capacity, especially increased antioxidant enzyme activity (e.g., SOD, CAT, and GPX), results in worse tumor status, although just as many of the exact opposite effects have been observed." (PMID 40426975, 2025). "emphasized the role of oxidative stress-related enzymes such as lactate dehydrogenase (LDH), catalase, and superoxide dismutase (SOD) in tumor tissues, showing that their expression levels correspond with mammographic findings and tumor characteristics." (PMID 41195270, 2025). "While SOD, CAT, HO-1, and NRF-2 highlight the intricate regulation of antioxidant defenses, MT and VIM emphasize their broader impact on tumor adaptation and aggressiveness." (PMID 40149643, 2025). "Through cascade catalytic reactions (CAT-, POD-, OXD-, and GSHOx-like), 131I-Mn/SAE@M reversed tumor hypoxia, enhanced ROS accumulation, and induced oxidative damage." (PMID 40968370, 2025). "Based on catalase activity, the nanozyme dissociated H2O2 into O2 molecules to relieve tumor hypoxia." (PMID 40666180, 2025). "We performed a tumor growth assay in vivo by comparing with the Ad-GFP group mice and showed that the tumor weights of the Ad-Catalase and Ad-GPX groups were much smaller." (PMID 39660100, 2025). "The only study on CAT activity in LSCC, conducted on 15 smoker patients, found higher enzyme activity in tumor tissues compared to tumor-free adjacent tissues, mirroring our findings." (PMID 40149643, 2025). "After intravenous injection, owing to the CAT properties of liposomes, this nano Pt breaks down the high concentration of H2O2 in the tumor to provide oxygen, thus enhancing the efficacy of PDT." (PMID 40486836, 2025). "For instance, porphyrin units can coordinate with metal ions like Cu2+ to mimic the activities of catalase (CAT) and glutathione peroxidase (GPx), helping to modulate the immunosuppressive tumor microenvironment (TME)." (PMID 41583445, 2025). "Curcumin (the yellow pigment of Curcuma longa) simultaneously suppressed NF-κB activation, up-regulated superoxide–dismutase and catalase, and decreased γ-H2AX formation across multiple tumor and normal cell lines." (PMID 41300514, 2025). "Tumor markers (AFP, CEA) and oxidative stress indices (MDA, 8-OHdG) were markedly decreased, while activities of hepatic antioxidants (SOD, CAT, GPx, GSH) were restored." (PMID 41228521, 2025). "Following the development of hypoxia, despite the high ROS production, tumor cells survive in that tumor microenvironment acquiring cell resistance mechanisms and inhibiting the antioxidant system as those of SOD and catalase." (PMID 39682125, 2024). "A cascadeenzyme system based on immobilized GOx and intrinsic catalase-likeactivity of H-CeO2 NPs was rendered on STA for enhancingthe effectiveness of PDT by elevation of ROS generation and alleviationof hypoxia in a tumor microenvironment." (PMID 38380497, 2024). "In tumor samples taken from the GSE45001 and GSE32879 datasets, seven genes (APOA2, CAT, ACOX1, APOE4, AGXT, EHHADH, and HSD17B4) showed a substantial downregulation." (PMID 38274331, 2024).
tumor (continued). "To date, catalase (CAT) and CAT-like enzymes are applied to catalyze the decomposition of H2O2 into water (H2O) and O2, to relieve tumor hypoxia." (PMID 38256096, 2024). "CAT-mimicking nanomaterials adequately leverage the over-produced H2O2 in TME as the O2 donor, thus theoretically displaying high tumor specificity and hypoxia-alleviating capability during the treatment of RIT." (PMID 38166931, 2024). "The catalytic activity enables NanoICD/CAT to decompose H2O2 and generate O2 effectively, thus providing the potential to alleviate tumor hypoxia and remodel immunosuppressive TME to enhance cancer immunotherapy." (PMID 38324678, 2024). "Resveratrol can inhibit the protective enzyme system in rapidly proliferating cancer cells, causing an imbalance in the expression levels and activities of SOD, CAT, and GPX in tumor cells." (PMID 39857347, 2024). "Simultaneously, the produced hydrogen sulfide can effectively inhibit CAT activity, resulting in an increased deposition of H2O2 at the tumor site." (PMID 39665080, 2024). "Compared with normal cells, tumor cells have lower levels of antioxidant enzymes, such as SOD, CAT, GPX, and GR, which hinder the detoxification process of free radicals and maintain high intracellular ROS levels." (PMID 38539798, 2024). "To determine if reducing ROS could preserve muscle morphology, we overexpressed ROS scavengers Catalase (Cat) and superoxide dismutase (Sod1), or antioxidative enzyme glutathione peroxidase 1 (GPx1, previously validated in), specifically in the muscles of tumour-bearing animals (QRasV12scribRNAi)." (PMID 38429578, 2024). "We analysed the changes in antioxidant (SOD1, SOD2, CAT, GPX1, HIF-1α, and NRF2) and anti-inflammatory nuclear factor kappa B (NF-κB) gene expression in tumour-bearing mice." (PMID 39506978, 2024). "In virtue of high-level H2O2 and the acidic TME, the photo-enhanced CAT/POD activity and photothermal effect of Ti3C2-MnO2-PDA enabled chemodynamic and thermal ablation of the tumor cells with a simultaneous supplement of oxygen." (PMID 39830353, 2024). "Mn2+ enhances MRI contrast, while H2S inhibits CAT activity, promoting H2O2 accumulation and enhancing ROS-mediated tumor cell apoptosis." (PMID 39665080, 2024). "As a result of these properties, NanoICD/CAT-PCA efficiently elicited protective cognate antitumor immunity against tumor rechallenge and tumor lung metastasis." (PMID 38324678, 2024). "CFAP with CAT‐, POD‐, and GPx‐mimic activities is successfully developed as a versatile tumor microenvironment modulators for reinforced redox dyshomeostasis." (PMID 38984397, 2024). "Significantly higher PI−CRT+ cell population was observed from the tumor sections of mice treated with NanoICD/BSA-PCA and NanoICD/CAT-PCA, which is consistent with the results obtained from immunofluorescence imaging." (PMID 38324678, 2024). "Catalase (CAT), a catalytic enzyme required to decompose H2O2 into O2, is essential for reducing tumor hypoxia." (PMID 39459028, 2024). "CAT catalyzes the generation of O2 from H2O2, alleviating tumour hypoxia and improving the efficiency of SDT." (PMID 38130720, 2023). "Catalase (CAT), a specific catalytic enzyme that is used to decompose H2O2 into O2, has been explored for the fabrication of nano-theragnostic for tumor treatment by the in-situ production of O2 combined with other therapeutic approaches." (PMID 37765212, 2023). "When applying relatively high concentrations of exogenous 1O2, secondary extracellular 1O2 generation is necessary for the optimal catalase inactivation and apoptosis-inducing intercellular ROS/RNS signaling of tumor cells." (PMID 38069213, 2023). "After transferring CAT-Ce6 to tumor tissues, OMV-aPDL1 can activate anti-tumor immune responses and dendritic cells (DCs) to induce CD8 T cells to move to tumor tissues." (PMID 37915541, 2023).
tumor (continued). "Discussion: Fe-MOF-5 has the function of simulating catalase, which can promote the decomposition of excessive H2O2 in the tumor microenvironment and produce oxygen to improve the hypoxic environment." (PMID 37064235, 2023). "Catalase-mimicking nanoceria oxidised H2O2 into O2 and Met inhibiting cellular respiration alleviated the hypoxic condition in deep tumour tissues." (PMID 36656411, 2023). "Compared with the tumor group consuming tap water, the DDW-consumed group reversed changes in all parameters except sialic acid, catalase, alanine transaminase, and aspartate transaminase." (PMID 36834518, 2023). "This unique composite material demonstrates exceptional catalase activity in decomposing H2O2 into O2, offering a significant advantage in mitigating tumor hypoxia." (PMID 37520291, 2023). "At the same time, CAT converted enriched H2O2 to oxygen, which solved the problem of tumor hypoxic resistance and boosted the efficacy of synergistic phototherapy." (PMID 37896240, 2023). "Metal oxides can show functions similar to catalase (CAT) and superoxide dismutase and are commonly used to design nano-delivery systems for tumor hypoxic microenvironment environments." (PMID 37575228, 2023). "Intriguingly, CAT‐engineered micro/nanomotors can consume overproduced endogenous hydrogen peroxide (H2O2, about 100 × 10−6 to 1 × 10−3m) in tumor cells to generate oxygen (O2) for their self‐propulsion." (PMID 37189219, 2023). "Further, the well-protected catalase within the NPs acted as an oxygen generator to decompose endogenous H2O2 and produce O2, thus improving tumor hypoxia and TME, and combining with chemotherapy to improve anti-tumor therapeutic effects." (PMID 37765212, 2023). "Although H2O2 can be converted to oxygen under the action of catalase, but the limited H2O2 in the tumor microenvironment also limits the intrinsic oxygen production." (PMID 37064867, 2023). "Targeting CAT, ASC, ASC2 transporters, PET imaging, MCF-7 Tumor (T/M = 4), intracranial tumor (T/B = 2) at 60 min p.i." (PMID 37895948, 2023). "The Ex-A loaded with catalase and sonosensitizer ICG had a high tumor-targeted ability and efficient BBB penetration, as well as a high accumulation in the tumor site, yielding enhanced sonodynamic therapy of glioblastoma." (PMID 37111742, 2023). "Therefore, the results show that catalase could be trapped in the tumor cell by ALG hydrogel for a long time to ameliorate hypoxic state, broke through the dependence of internal radiotherapy on oxygen, optimized internal radiotherapy efficacy, and eliminate local solid tumors." (PMID 37899463, 2023). "Alcohol dehydrogenase 1A (ADH1A), CAT, GAPDH, and MDH2 were related to the generation of precursor metabolites and energy, which played an important role in the proliferation of tumor cells." (PMID 37124724, 2023). "CAT-Ce6 has the catalytic activity of CAT, which can decompose H2O2 in tumor tissues to generate oxygen to improve the hypoxic state, thereby enhancing the photodynamic killing effect on tumors." (PMID 37915541, 2023). "Catalase and GSH, with significantly increased MDA levels, subsequently increased the tumor biomarkers (AFP and CEA)." (PMID 36850982, 2023). "In our study, the treatment with pepper fruit extracts promoted a substantial increase of catalase activity in the two cell lines, which could scavenge the high H2O2 concentrations which lead to cancer-associated oxidative stress, and help to arrest the tumor’s evolution." (PMID 37507999, 2023). "MnO2 with a catalase-mimic catalytic activity can catalyze overexpressed H2O2 in tumors to generate O2, thus relieving tumor hypoxia 148-150." (PMID 36632234, 2023). "The interplay between SOD/catalase and active NOX1 in tumor cells enables selective apoptosis induction when the protective system is disrupted, offering the potential for selective tumor cell apoptosis in vitro and in vivo." (PMID 38069213, 2023).
tumor (continued). "Future work localizing catalase to other subcellular compartments such as mitochondria, the nucleus, or tethering to the plasma membrane may produce different effects and further elucidate the spatial importance of antioxidant expression and hydrogen peroxide localization in tumor growth." (PMID 37311396, 2023). "As we have designed, we were expected to utilize the CAT, which can catalyze H2O2 to produce O2 to enhance Au@MSN-Ter/THPP@CM NPs induced photodynamic reactions in the tumor cells." (PMID 37273798, 2023). "CAT triggered rapidly decomposed of H2O2 to produce O2, and thus the hypoxia status in tumor microenvironment was improved." (PMID 35119544, 2022). "Since H2O2 can be decomposed to form O2 and H2O by catalase (CAT) or nanozymes, many nanoplatforms are developed to utilize H2O2 as oxygen generator to address tumor hypoxia." (PMID 36145513, 2022). "On the other hand, HSP (20 mg/kg body weight/day) supplementation on DMH treated rat decreases tumour multiplicity through the upregulation of antioxidant enzymes SOD, CAT, GPx." (PMID 35128104, 2022). "The obtained nanocapsules preserved the enzyme activity of CAT, as an oxygen generator can decompose H2O2 in tumor to relieve hypoxia for enhanced PDT." (PMID 35624636, 2022). "Tumor and inflammatory markers (except CRP) correlated positively with GSSG, GSSG/GSH ratio, 8-oxodG and F2-IsoPs, and negatively with CAT and GSH." (PMID 36232966, 2022). "CAT and H2O2 were separately encapsulated within stealthy liposomes for a long-lasting effect in tumor re-oxygenation enhancement." (PMID 36873299, 2022). "The dry acetone extract acted as a pro-oxidant, causing intense ROS production, and thus stimulating the enzymatic activity of SOD, CAT, and GPx in CAL-27 tumor cells." (PMID 36290658, 2022). "The TMNSs generate a large concentration of H2O2 and release ̇OH, which has the capability to destroy tumor cells, while TMNSs in normal cells (alkaline condition) produce a small amount of H2O2, which is decomposed by catalase." (PMID 36505711, 2022). "Nanozymes with CAT- or SOD-like activity can catalyze the generation of O2 and alleviate the hypoxia tumor microenvironment, and thus have been broadly used." (PMID 35384520, 2022). "Consistent with the results from HCC cell lines, the total membrane CAT and P4HB expression were higher in HCC tissues compared with adjacent non-tumor tissues." (PMID 35392238, 2022). "Because of the low expression of catalase in tumor cells, the ability to clear H2O2 in tumor tissue is weaker than in normal tissue." (PMID 36139668, 2022). "Nanozymes that are more widely used in tumor therapy are peroxidase (POD), oxidase (OXD), catalase (CAT), and superoxide dismutase (SOD)." (PMID 36531332, 2022). "CAT, an extraneous heme-containing enzyme that can rapidly decompose H2O2 into H2O and O2, is a highly suitable candidate for increasing tumor oxygenation." (PMID 35624636, 2022). "On the other hand, the identified genes with notable decreased mRNA levels playing roles in tumor growth promotion were USP12, CAT and PTK2 (FAK)." (PMID 36077645, 2022). "(III) Endogenous hyaluronidases (HAase) induce the in-situ disassembly of CAT@HA-HMME NPs in tumor, leading to the release of HA-HMME and CAT." (PMID 35387175, 2022). "Due to CAT-mediated decomposition of H2O2, additional O2 was generated for relieving hypoxic tumor microenvironment." (PMID 35119544, 2022). "ECA pull-down followed by mass spectrometry further showed that there was significantly less expression of ECA binding membrane catalase (CAT) and prolyl 4-hydroxylase beta polypeptide (P4HB) in HCC tissues compared with the adjacent non-tumor tissues." (PMID 35392238, 2022). "The designed nanoparticles can not only encapsulate CAT and transport it into the tumor but also decompose tumor endogenous H2O2 to generate oxygen, overcome tumor hypoxia and greatly improve the therapeutic effect of PDT on solid tumors." (PMID 36147526, 2022).